NUDT2 (nudix hydrolase 2)
Description:
Catalyzes the asymmetric hydrolysis of diadenosine 5',5'''-P1,P4-tetraphosphate (Ap4A) to yield AMP and ATP (By similarity). Exhibits decapping activity towards FAD-capped RNAs and dpCoA-capped RNAs in vitro (By similarity).
Synonyms: APAH1; IDDPN
Tractability: Small molecule: a structure with a bound ligand is known; it has a binding pocket of medium quality. PROTAC: ubiquitination databases record sites on it; its protein half-life has been measured.
Target class: Enzyme; Hydrolase
Gene: Protein-coding gene on chromosome 9 (34,329,506 to 34,343,713, forward strand). Ensembl gene ENSG00000164978.
Subcellular location (Human Protein Atlas): Nucleoplasm
Pathways (Reactome):
Cellular responses to stimuli: Detoxification of Reactive Oxygen Species
Gene Ontology:
Molecular function: protein binding; bis(5'-nucleosyl)-tetraphosphatase (asymmetrical) activity; bis(5'-nucleosyl)-tetraphosphatase (symmetrical) activity; bis(5'-nucleosyl)-tetraphosphatase activity; hydrolase activity
Biological process: AMP biosynthetic process; apoptotic process; ATP biosynthetic process; cellular response to oxidative stress; nucleobase-containing compound metabolic process
Cellular component: mitochondrial matrix
Genetic constraint (gnomAD): Loss-of-function variants: 12 observed, 15.19 expected, observed/expected ratio (o/e) 0.79, 90% interval 0.5 to 1.28. The upper end of that interval is the gene's LOEUF score, 1.28, which puts it in group 5 of 6, group 1 being the genes least tolerant of losing a copy. Missense variants: 167 observed, 184.51 expected, observed/expected ratio (o/e) 0.91, 90% interval 0.8 to 1.03. Synonymous variants: 67 observed, 71.53 expected, observed/expected ratio (o/e) 0.94, 90% interval 0.77 to 1.15.
Homologues: Orthologues: chimpanzee NUDT2 (100% identical), macaque NUDT2 (97% identical), rabbit NUDT2 (91% identical), dog NUDT2 (90% identical), mouse Nudt2 (89% identical), pig NUDT2 (88% identical), rat Nudt2 (88% identical), guinea pig NUDT2 (85% identical), tropical clawed frog nudt2 (61% identical), zebrafish nudt2 (53% identical), Caenorhabditis elegans ndx-4 (48% identical).
Diseases named in the same sentence as NUDT2 in open-access papers:
NUDT2 is named in the same sentence as 25 diseases in open-access papers, as found by Europe PMC text mining. Sharing a sentence is not in itself a finding about the gene and the disease. The quoted sentences say what the papers report.
breast carcinoma (7 papers, 2015 to 2025). "Recent studies have demonstrated that NUDT2 is closely linked to breast cancer, intellectual disabilities, and peripheral neuropathy." (PMID 40697080, 2025). "Nudt2 has been found to be associated with RAG proteins which are involved in mTOR activation in breast cancer cells." (PMID 38715773, 2024). "In this study we examined the role of Nudt2 in breast carcinoma through its expression in human invasive ductal carcinoma tissues, and its functions in human triple negative breast cancer (TNBC) cell lines." (PMID 38715773, 2024). "Previously it was reported that Nudt2 is involved in breast cancer proliferation by regulating mTORC1 localization." (PMID 38715773, 2024). "A recent study has revealed that Nudt2 was significantly higher in ductal breast carcinoma tissue compared to healthy tissue, highlighting this protein’s potential as a prognostic factor in human breast carcinomas." (PMID 38715773, 2024). "It was recently discovered that Nudt2 has a significant role in promoting breast cancer proliferation by different mechanisms involving estrogen." (PMID 38715773, 2024). "This study also showed Nudt2 to be an estrogen-repressed gene that is induced by HER2 pathways in breast carcinoma cells thereby promoting proliferation." (PMID 38715773, 2024). "In this study, Nudt2 was shown to have a significant role in promoting breast cancer proliferation by different mechanisms from estrogen." (PMID 37445693, 2023). "High expression levels of Nudt2 has been observed in breast cancer and it has been shown to affect cell proliferation." (PMID 37445693, 2023). "Nudt2 was shown to be involved in cell proliferation in breast cancer, making it an important target in cancer therapy." (PMID 37445693, 2023). "Nudt2 promotes proliferation of breast carcinoma cells in vitro, and is a potent prognostic factor in human breast carcinomas, under a different mechanism of estrogen." (PMID 37445693, 2023). "Nudt2 has been demonstrated to have a role in breast cancer proliferation by regulating mTORC1 localization and activity which are regulated by Nudt2 and RagGTPase interactions." (PMID 37445693, 2023). "As previously shown, Nudt2 regulates cell proliferation in breast cancer cell lines via its effect on mTORC1 activity." (PMID 37445693, 2023). "All these studies showing the importance of Nudt2 in regulation of breast cancer proliferation under different mechanisms led us to study its roles in melanoma." (PMID 37445693, 2023). "It has also been shown that the level of NUDT2 expression positively correlates with lower survival and increased lymph node metastases in breast carcinoma." (PMID 27144453, 2016). "Nudt2 could also promote the proliferation of breast carcinoma cells through a decrease in the intracellular Ap4A level." (PMID 38715773, 2024). "Building upon these findings that Nudt2 promotes proliferation and might serve as a valuable and potential prognostic marker in human breast carcinomas, our main objective in the present study was to explore the role of Nudt2 in TNBC cells." (PMID 38715773, 2024). "Recent research supports Nudt2’s role in the regulation of cellular proliferation in breast cancer." (PMID 37445693, 2023). "Knockdown of Nudt2 suppressed proliferation of several breast carcinoma cell lines by regulating mTROC1 activity via physical interaction with RagGTPases, suggesting that Nudt2 inhibition could have strong anti-tumor effects." (PMID 37445693, 2023). "Our results expand upon the earlier demonstration that NUDT2 promotes proliferation of breast carcinoma cells and that NUDT2 status could be a useful prognostic marker." (PMID 27144453, 2016). "Among the other genes that we linked to late stage disease, little is known about their potential roles in other cancers although NUDT2 has previously been shown to be upregulated in human breast carcinomas whereas SNX5 is upregulated in papillary thyroid carcinomas." (PMID 25889361, 2015).
breast carcinoma (continued). "In our present study, higher expression levels of Nudt2 were detected in human IDC tissues, linking it to the promotion of proliferation of breast carcinoma cells." (PMID 38715773, 2024). "NUDT1, NUDT2, NUDT5, and NUDT16 were overexpressed in breast cancer tissue." (PMID 40839607, 2025).
chronic myelogenous leukemia (3 papers, 2016 to 2023). "A previous report showed that Nudt2 knockout in chronic myelogenous leukemia cells regulate many genes involved in tumorigenesis and metastasis indicating that Nudt2 may have a major role in tumorigenic potential of cancer cells." (PMID 37445693, 2023). "For example, RNA-seq gene expression and subsequent network analysis in chronic myelogenous leukemia cells in culture highlighted the potential of NUDT2 as a therapeutic target, as inhibition of NUDT2 significantly affected gene pathways involved in metastasis, invasion, and apoptosis." (PMID 33668737, 2021). "RNAseq analysis in KBM-7 chronic myelogenous leukemia cells with or without Nudt2 knockdown indicated Nudt2 involvement in cell proliferation, invasion and metastasis." (PMID 37445693, 2023).
Intellectual disability (3 papers, 2023 to 2025). "Our results supported that variants in the NUDT2 cause a multisystem disease with intellectual disability and polyneuropathy, and more research is needed to study the underlying mechanisms of NUDT2-related disorders and the genotype-phenotype correlations." (PMID 38243213, 2024). "Bi-allelic loss of function variants in NUDT2 has recently been reported as a rare cause of intellectual disability (ID)." (PMID 38243213, 2024).
melanoma (2 papers, 2023 to 2024). A malignant, usually aggressive tumor composed of atypical, neoplastic melanocytes. "The tumors in mice injected with CHL−1 Nudt2 knockdown cells grew at a slower rate and had a smaller volume than the tumors in mice injected with control melanoma cells." (PMID 37445693, 2023). "Further investigation is needed to understand the molecular mechanism behind the effect of Nudt2 on anchorage-independent growth in melanoma." (PMID 37445693, 2023). "Our study showed that Nudt2 knockdown suppressed anchorage-independent growth of human melanoma cells in vitro." (PMID 37445693, 2023). "We found in our recent study that Nudt2 knockdown suppressed anchorage-independent growth of human melanoma cells in vitro, and its effect in vivo was determined by investigating the role played by Nudt2 knockdown on the ability of the cells to form tumors in a mice xenograft model." (PMID 38715773, 2024). "The goal of this study was to examine the role of Nudt2 in melanoma cells and in vivo model." (PMID 37445693, 2023). "In melanoma, Nudt2 appears to be a tumor-promoting gene that could be utilized as a cancer therapy target." (PMID 37445693, 2023). "A wound scratch model was used to test the migration of melanoma Nudt2 knockdown cell lines." (PMID 37445693, 2023). "The purpose of this study was to find out whether Nudt2 has an effect on anchorage-independent growth in melanoma cell lines." (PMID 37445693, 2023). "Thus, Nudt2 plays an important role in promoting anchorage-independent growth and cell migration in melanoma." (PMID 37445693, 2023). "Here, we investigated whether Nudt2 plays a role in melanoma cell growth by first lowering Nudt2 levels in these cells." (PMID 37445693, 2023). "Moreover, we showed that Nudt2 overexpression increased anchorage-independent growth in human melanoma cells." (PMID 37445693, 2023). "Thus, the main goal of the present study is to explore the role played by Nudt2 in melanoma cell function by using in vitro assays and the xenograft model." (PMID 37445693, 2023). "Therefore, we investigated the role played by Nudt2 in the growth of human melanoma." (PMID 37445693, 2023). "NOD/SCID mice were subcutaneously injected with either control CHL−1 melanoma cells or Nudt2 knocked down IVIS; the analysis revealed a significant difference in tumor growth between the control and Nudt2 knockdown groups (p = 0.032)." (PMID 37445693, 2023). "In this study, we found that Nudt2 knockdown inhibited anchorage-independent melanoma growth but without any effect on cell proliferation, and its knockdown reduced tumor growth in vivo." (PMID 37445693, 2023). "Control and Nudt2-knocked down human melanoma cell line (CHL−1) were produced using either non-targeting or Nudt2-specific shRNA lentiviral particles." (PMID 37445693, 2023). "Currently, the function of Nudt2 in malignant melanoma has not been demonstrated." (PMID 37445693, 2023).
polyneuropathies (2 papers, 2023 to 2024). "The four patients presented in the third and fourth studies with homozygous p.A63Qfs*3 in NUDT2 also developed polyneuropathy in addition to ID." (PMID 38243213, 2024).
breast invasive ductal carcinoma (1 paper, 2024). "A significantly higher expression of Nudt2 was observed in human invasive ductal carcinoma tissues compared to that in normal breast tissue." (PMID 38715773, 2024). "Nudt2 immunoreactivity was evaluated in two sets of human breast invasive ductal carcinoma (IDC) tissues." (PMID 38715773, 2024). "Based on the results of Nudt2 expression in the two sets of human breast invasive ductal carcinoma (IDC) tissues." (PMID 38715773, 2024).
dementia (1 paper, 2023). Loss of intellectual abilities interfering with an individual's social and occupational functions. "Five autoantibodies (CAMK2A, CKS1B, ETS2, MAP4, and NUDT2) were dysregulated in both dementia and MCI." (PMID 38107644, 2023). "Of these significantly positively correlated autoantibodies, five were differentially expressed in dementia and included CL1A, CBFA2T3, PKLR, APPL1, and NUDT2, whilst two were dysregulated in MCI including ABI1 and NUDT2." (PMID 38107644, 2023). "Five autoantibodies were commonly dysregulated in both dementia and MCI, including anti-CAMK2A, CKS1B, ETS2, MAP4, and NUDT2." (PMID 38107644, 2023). "Five autoantibodies in particular, were dysregulated in dementia and MCI, including CAMK2A, CKS1B, ETS2, MAP4, and NUDT2." (PMID 38107644, 2023). "There is limited research on the role of NUDT2 and EST2 in dementia." (PMID 38107644, 2023).
encephalitis (1 paper, 2021). An acute inflammatory process affecting the brain parenchyma. "We proceeded to infect Nudt2+/+ and Nudt2−/− mice with VSV using an intranasal infection regime, causing encephalitis." (PMID 34824277, 2021).
poliovirus infection (1 paper, 2016). An disease or disorder caused by infection with Enterovirus C. "Poliovirus infection is known to cause a slight (2-fold) increase in Ap4A while the SARS coronavirus protein 7a physically interacts with NUDT2, although the effect of this on the level of Ap4A is not known." (PMID 27144453, 2016).
virus infections (1 paper, 2021). "To test whether NUDT2 deficiency may generally affect vulnerability to virus infections, we performed an unbiased proteome analysis of Nudt2−/− and Nudt2+/+ bone marrow cells." (PMID 34824277, 2021). "The expression of NUDT2 protein, however, does not change after cytokine treatment or virus infection." (PMID 34824277, 2021).
cancer (7 papers, 2015 to 2025). A tumor composed of atypical neoplastic, often pleomorphic cells that invade other tissues. "Soft agar colony formation was performed with MDA-MB-231 and MDA-MB-436 cell lines to assess the behavior of cancer cells with reduced Nudt2 expression." (PMID 38715773, 2024). "Thus, in breast carcinoma cell lines, it was found that knocking down NUDT2 led to reduced cell proliferation and an accumulation of cells in the G0/G1 phase of the cell cycle, further highlighting Ap4A’s role in regulating cancer cell growth." (PMID 40807231, 2025). "Taken together, there seems to be sufficient evidence to support NUDT2 as a novel chemotherapeutic target that could conceivably exert an anti-cancer effect via multiple pathways involving apoptosis, metastasis, invasion and immunosuppression." (PMID 27144453, 2016). "Regardless, our results suggest that the NUDT2 protein could be a novel cancer chemotherapeutic target, with its inhibition potentially exerting strong anti-tumor effects via multiple pathways involving metastasis, invasion, immunosuppression and apoptosis." (PMID 27144453, 2016). "From a therapeutic standpoint, this opens new opportunities: targeting Ap4A metabolism—either by inhibiting NUDT2 or administering stable Ap4A analogs—could modulate gene expression in a way that suppresses tumorigenesis or sensitizes cancer cells to treatment." (PMID 40807231, 2025). "The potential of NUDT2 as a pleiotropic therapeutic target for cancer simultaneously affecting metastasis, invasion, apoptosis, immunosuppression and inflammation certainly warrants further investigation and validation in different cancer cells and animal models." (PMID 27144453, 2016). "In addition, many of the most strongly affected genes have roles in promoting cancer metastasis and invasion, suggesting that NUDT2 may offer a novel, pleiotropic target for cancer chemotherapy." (PMID 27144453, 2016). "RALGPS1, NUDT9, NUDT2, and PDE4A were less expressed in cancer cell lines; JUP, ADA, HPRT1, and IMPDH1 were highly expressed in cancer cell lines in CCLE." (PMID 34745385, 2021). "Although NUDT2 was overexpressed only in a subset of cancers, NUDT4 was downregulated in all cancers and appeared to be highly expressed throughout all normal tissues." (PMID 29142246, 2017). "We confirm previously known cell cycle perturbations upon NUDIX depletion such as NUDT2 and NUDT5 in cancer cells, characterized by an accumulation in G1 (2 N) phase." (PMID 29142246, 2017).
tumor (5 papers, 2016 to 2024). "Association between Nudt2% expression in tumor (%Ex Tumor) and in normal tissues (%Ex Normal) and various clinicalpathological parameters IDC patients." (PMID 38715773, 2024). "Nudt2 expression levels correlated with (TNM) system which refers to the international standard for classifying the malignant of a tumor based on factors: tumor (T), node (N) and metastases (M)." (PMID 38715773, 2024). "The difference in tumor volume between the control and Nudt2 knockdown groups was significant, with a p value of 0.006." (PMID 37445693, 2023). "Tumor volume in the Nudt2 knockdown group was lower than that of the control group, with a reduction of 96%." (PMID 37445693, 2023). "In order to explore whether Nudt2 knockdown affects tumor growth in vivo, we used a xenograft tumor model." (PMID 37445693, 2023). "Nudt2 knockdown significantly suppressed tumor growth in this model." (PMID 37445693, 2023). "Interestingly, NUDT2 may be a candidate tumor suppressor gene." (PMID 34745385, 2021). "All patients in the study were categorized as no metastases at diagnosis (M0), tumor (T) stage 1-2, nodal involvement (N) stages 0-1 and Grades 2-3.Our findings revealed that Nudt2 expression showed higher expression in 90% of the IDC cases that assessed in both sets." (PMID 38715773, 2024).
infection (3 papers, 2021 to 2024). The state of being infected such as from the introduction of a foreign agent such as serum, vaccine, antigenic substance or organism. "Similarly shown for PRRs, the in vivo phenotype of NUDT2 may only be visible when using sophisticated in vivo models or when specific infection models are used." (PMID 34824277, 2021). "Surprisingly, despite significant growth differences in cell culture experiments, the infection in vivo did not lead to significant differences in survival rates when comparing Nudt2+/+ and Nudt2−/− mice." (PMID 34824277, 2021).
neurodevelopmental disorder (1 paper, 2024). A behavioral and cognitive disorder with onset during the developmental period that involves impaired or aberrant development of intellectual, motor, or social functions. "The missense mutation p.I65R reported here resides in a conserved region near the Nudix box domain but may not define pathogenic LOF alleles, thereby differential activities of the protein placing NUDT2-related disease towards the milder phenotypes of neurodevelopmental disorders." (PMID 38243213, 2024).
NUDT2 also shares sentences with these, for which no sentence is quoted: breast invasive carcinoma (1 paper); chondropathies (1); lymph node metastases (1); microcephaly (1); Neurodevelopmental delay (1); non-small cell lung carcinoma (1); Obesity (1); papillary thyroid carcinomas (1); peripheral neuropathy (1); Sepsis (1); triple-negative breast carcinoma (1).